PVT1 (Pvt1 oncogene)
Diseases named in the same sentence as PVT1 in open-access papers (continued):
Sharing a sentence is not in itself a finding about the gene and the disease.
tumor (continued). "Indeed, PVT1/circPVT1-mediated immune suppression is a challenge for those therapies aiming at restoring effective anti-tumor immune responses, including monoclonal antibodies (e.g.." (PMID 32228602, 2020). "Thus, we have extended this previous work, we assessed PVT1 levels using R-Scope ISH in a large patient TMA (paired tumor and adjacent normal tissues from 792 patients)." (PMID 33076512, 2020). "Knockdown of PVT1 obviously inhibited the tumor development." (PMID 33067424, 2020). "High PVT1 expression was associated with larger tumor size, deeper tumor invasion, a higher frequency of lymph node metastases, and short survival duration." (PMID 33076512, 2020). "Meanwhile, our deepen study suggests that PVT1 acts as a significant tumor regulator and PVT1-miR-194-5p-BCLAF1 axis participates in BC progression, which emerges its possibly clinical application of BC as a meritoriously clinical diagnosis and treatment strategies." (PMID 33188158, 2020). "To further determine whether PVT1 inhibition by PVT1 ASO affects tumor growth in vivo, we injected GA0518 cells (with high PVT1 expression) subcutaneously into the back of the mice to form a PDX model." (PMID 33076512, 2020). "In CC, studies revealed that PVT1 acts as a sponge or ceRNA for miR-424, this miRNA may act as a novel tumor suppressor in CC by blocking cell growth through targeting the KDM5B-Notch pathway." (PMID 33371204, 2020). "PVT1 promoted tumor cell metastasis by upregulating autophagy." (PMID 33050642, 2020). "This heterogeneity in isoform expression needs to be considered when studying the role of PVT1 in carcinogenesis, as the biology of each isoform might have a different impact on tumor initiation/progression and patient survival." (PMID 32083000, 2020). "Here, the up-regulated expression of lncRNA PVT1 is found in our PDAC tumor samples." (PMID 32201527, 2020). "We found that PVT1 expression was significantly correlated with clinical stage and tumor size." (PMID 32021563, 2020). "Tumor xenografts experiments suggested that silencing PVT1 sensitized NSCLC (Non-small-cell lung carcinoma) cells to radiotherapy in vivo, and this could be reverted by miR-195 inhibitor." (PMID 32117705, 2020). "Moreover, PVT1 controls the immunosuppressive activity of granulocytic MDSC (G-MDSC) in tumor-bearing mice." (PMID 32878637, 2020). "Overall, it appears that many PVT1-regulated miRNAs may have a protective effect against tumor growth and proliferation." (PMID 31249809, 2019). "We explored whether the tumor microenvironment might regulate the expression of Pvt1 in G-MDSCs, and which factor likely regulates the Pvt1 level." (PMID 30925926, 2019). "We also detected the expression of Pvt1 in G-MDSCs and M-MDSCs and found that the expression level of Pvt1 was not significantly different between G-MDSCs and M-MDSCs from the bone marrow, spleen and tumor tissues." (PMID 30925926, 2019). "Therefore, PVT1 participates in the downstream angiogenesis-related signaling pathway of c-Myc and can promote tumor angiogenesis." (PMID 31309249, 2019). "In fact, genomic co-amplification of MYC and PVT1 has been reported in different types of tumor." (PMID 31781490, 2019). "In addition, PVT1 acts as a sponge for miR-126 and increases the expression of energy metabolism-related enzyme SLC7A5 in mitochondria, which is another important mechanism through which PVT1 enhances energy metabolism and promotes tumor cell proliferation." (PMID 31380270, 2019). "Less evidence, however, also supports a potential role of PVT1 as a tumor suppressor." (PMID 31781490, 2019).
tumor (continued). "The role of circ-PVT1 in PTX resistance of GC in vivo was measured by xenograft tumor model." (PMID 31793989, 2019). "Interestingly, we viewed that circ-PVT1 down-regulation reinforced PTX-induced anti-tumor effect in vivo." (PMID 31793989, 2019). "Furthermore, HP1γ-induced downregulation of the LRF/ZBTB7A favors the expression of several tumor-promoting factors, such as AXL receptor tyrosine kinase (AXL), plasmacytoma variant translocation 1 (PVT1), and ETS Like-1 protein (ELK1)." (PMID 31823818, 2019). "PVT1 can promote tumor proliferation by downregulating the expression of p15 and p21." (PMID 31309249, 2019). "PVT1 up-regulation in CRC promotes tumor cell proliferation, invasion, and metastasis." (PMID 31598169, 2019). "Several studies have confirmed that PVT1, as a potential oncogene, can promote tumor proliferation." (PMID 31380270, 2019). "Additionally, in some tumor tissues, the region near the PVT1 promoter shows more pronounced structural changes than other lncRNA promoters, such as deletions, inversions, or duplications, which alter the chromatin and TAD environment of the PVT1 promoter." (PMID 31309249, 2019). "It has also been shown that PVT1 plays an important role in autophagy in tumor cells." (PMID 31380270, 2019). "Conversely, when PVT1 is knocked down, tumor cell viability decreases, and apoptosis increases." (PMID 31249809, 2019). "Knocking down either Myc or PVT1 decreases proliferation of Myc/PVT1/Ccdc26/Gsdmc mutant tumor cells to the same extent as knocking down both PVT1 and Myc, thus suggesting the presence of a common oncogenic pathway shared by Myc and PVT1 in tumor initiation." (PMID 31497532, 2019). "Overexpression of PVT1 attenuated gemcitabine-mediated inhibition of tumor growth." (PMID 31508377, 2019). "PVT1 lncRNA gene is up-regulated in all tumor types studied." (PMID 30809433, 2019). "Additionally, lncRNA Pvt1 knockdown reduced the ability of G-MDSCs to delay tumor progression in tumor-bearing mice in vivo." (PMID 30925926, 2019). "These discoveries point to a direction for the study of PVT1 and tumor development." (PMID 31380270, 2019). "In addition, the expression of PVT1 as measured by qPCR in tumor tissues showed significant reduction when treated with PVT1 ASO compared with the control ASO group." (PMID 31601234, 2019). "Interestingly, similar microenvironmental factors (e.g., IL-6 or tumor-associated factors) can induce the overexpression of lnc-C/EBPβ, lnc-CHOP, Olfr29-ps1, Pvt1, and RNCR3 in MDSCs." (PMID 31404149, 2019). "All these data indicate that lncRNA Pvt1 is highly expressed in G-MDSCs from tumor tissues." (PMID 30925926, 2019). "We found that the proportion of CTLs in dLNs from the si-Pvt1 group was much higher than that in dLNs from the si-NC group, and the proportions of CTLs and Th1 cells in tumor tissues exhibited a moderate increase in the si-Pvt1 group compared with the si-NC group." (PMID 30925926, 2019). "In Han GC, PVT1 was correlated with lymph node metastasis and primary tumor site." (PMID 30679629, 2019). "Higher expression of PVT1 lncRNA was closely correlated with higher tumor stage and poor prognosis." (PMID 31601234, 2019). "The exact biogenesis of lncRNA PVT1 is not characterized, but its association with factors like cell differentiation, metastatic disease, overall survival, and tumor stage, among other characteristics, has been widely studied." (PMID 31249809, 2019). "The expression of Pvt1 was higher in tumor-infiltrating G-MDSCs than in splenic G-MDSCs." (PMID 30925926, 2019). "In addition, knockdown of lncRNA Pvt1 delayed tumor progression in tumor-bearing mice by inhibiting the function of G-MDSCs." (PMID 31448238, 2019). "Several other lncRNAs have also been shown to function as oncogenes through sponging miRNAs and positively regulating their target tumor-promoting genes, including CCAT1, NEAT1, plasmacytoma variant translocation 1 (PVT1), small nucleolar RNA host gene 1 (SNHG1), UCA1, and XIST." (PMID 30223861, 2018).
tumor (continued). "Additionally, lncRNA knockdown studies have revealed a role for growth arrest-specific 5 (GAS5) in tumor cell quiescence and the modification of cell proliferation and PVT1 oncogene (PVT1) in the regulation of apoptosis and cell proliferation." (PMID 30060501, 2018). "Serum levels of PVT1 were also compared among patients with different sizes of tumor." (PMID 29760583, 2018). "Serum level of PVT1 increased with the increased sizes of primary tumor." (PMID 29760583, 2018). "We have reported, for the first time, the effects of PVT1 on the radiosensitivity of tumor cells, and have preliminarily explored the molecular mechanisms of the influence of PVT1 on NPC radioresistance; however, the specific activation pathways need further elucidation." (PMID 29445147, 2018). "Moreover, LASP1 was found to be downregulated after knockdown of PVT1 and overexpression of LASP1 attenuated the tumor-suppressive roles of PVT1 knockdown." (PMID 28404954, 2017). "Furthermore, the correlation of both pvt1 and myc duplication in almost every tumor bearing myc amplification are in favor of this co-dependence." (PMID 28637507, 2017). "PVT1 is aberrantly expressed in many tumor types, and was reported as a candidate oncogene." (PMID 28969069, 2017). "siRNA-mediated gene silencing and entire PVT1 gene vector mediated gene overexpression were respectively used to assess the effects of lncRNA PVT1 on cell proliferation and invasion in vitro, and tumor formation in vivo." (PMID 29046366, 2017). "PVT1 is a candidate oncogene in many tumor types, including lung, gastric, and prostate cancers." (PMID 28969069, 2017). "Knockdown of PVT1 suppressed tumor growth in vitro and in vivo." (PMID 28404954, 2017). "Altogether, our data further supported that knockdown of PVT1 suppressed ESCC tumor growth in vivo." (PMID 28404954, 2017). "In addition, the level of PVT1 expression was positively related to tumor size, TNM stage, lymph node metastasis and distant metastases." (PMID 29348896, 2017). "In addition, in vivo experiments showed that PVT1 knockdown repressed xenograft tumor growth, while Mcl-1 overexpression partially rescued xenograft tumor growth." (PMID 29254209, 2017). "Some lncRNAs (e.g., lncBRM, lncTCF7 and PVT1) play regulatory roles in the maintenance of stemness properties of LCSCs and hence may have a role in tumour initiation (Table." (PMID 29061150, 2017). "Expression of miR-203 in ESCC tumor tissues inversely correlated with that of PVT1." (PMID 28404954, 2017). "Compared to the MG-63-vector group, tumor growth was reduced in the si-PVT1#1 group." (PMID 27813492, 2016). "The result suggest that PVT1 plays different functional roles in normal and tumor state." (PMID 27580177, 2016). "What’s more, lncRNAs may serve as tumor markers and therapeutic targets, such as PVT1, Xist, ATB and MALAT1." (PMID 27328915, 2016). "qRT-PCR analysis was performed to detect the average expression of PVT1 in tumor tissues." (PMID 25890171, 2015). "Interestingly, primary PVT1 transcripts are significantly expressed in prostate tissues but mature miR-1206 expression was found to be undetectable in primary normal and tumor prostate samples." (PMID 23077621, 2012). "Furthermore, both the MYC and the PVT1 genes are frequent targets for retroviral integration in mouse tumour assays." (PMID 21814516, 2011). "Whereas up to seven co-mutations can be found in a single tumor, in over 2,000 tumors none had insertions into both the Myc and Pvt1 loci." (PMID 18194563, 2008). "Therefore, an evolutionarily new tumor-specific sequence with a high potential of oncogenicity is presented in the mammalian lineage near Pvt1 locus." (PMID 17189608, 2006). "Additionally, depletion of the long noncoding RNA (lncRNA) plasmacytoma variant translocation 1 (PVT1) secreted by nonmyelinating Schwann cells inhibits tumor growth in PDAC." (PMID 40567365, 2025). "Future research may identify lncRNA PVT1 as a novel therapeutic target for tumor resistance." (PMID 40191723, 2025).
tumor (continued). "In this study, we tackled this question by genetically dissecting the locus of Pvt1, a tumor suppressive lncRNA, which has been shown to negatively regulate in cis the transcription of the neighboring Myc proto-oncogene in response to stress and during tumor development." (PMID 40743223, 2025). "Within the context of aerobic glycolysis, known as the Warburg effect, PVT1 assumes a critical role, potentially orchestrating the expression and functionality of essential enzymes in the glycolytic pathway to fulfill the heightened energy demands of rapidly dividing tumor cells." (PMID 39286016, 2024). "Moreover, PVT1 modulates the metabolic landscape of tumor cells by adjusting key metabolites in the tumor microenvironment, such as lactate and pyruvate, which in turn serve as signaling entities influencing tumor cell conduct." (PMID 39286016, 2024). "Thus, we hypothesized that PVT1 inhibition might help to stimulate anti-tumor immunity in HNSCC in addition to eliminating CSCs." (PMID 36894542, 2023). "Furthermore, PVT1 contributes to tumor development by targeting miR-519d-3p/HIF-1A in PAAD." (PMID 36882663, 2023). "Indeed, different reports support the possibility that the PVT1 transcript may sequester miRNAs with tumor-suppressive functions, thus leading to the activation of proliferative and survival pathways and the acquisition of metastatic traits." (PMID 36901971, 2023). "However, there are few studies on the relationship between PVT1 and tumor cells metabolism." (PMID 36941464, 2023). "Indeed, a significant amplification of PVT1 alone was found in some tumour types, suggesting that increased PVT1 expression may be sufficient to increase MYC levels, which is crucial in tumorigenesis." (PMID 34754096, 2022). "Therefore, we examined whether PVT1 could regulate the migration and invasion ability of tumor cells." (PMID 35664988, 2022). "In vivo assay confirmed that PVT1 knockdown could repress CC tumor growth." (PMID 33817293, 2021). "However, more data are required to elucidate the functions of PVT1 in tumor progression." (PMID 34922601, 2021). "Previous study found that PVT1 could regulate E2F1 expression levels in tumor development." (PMID 33750300, 2021). "In addition, the effect of PVT1 on CC tumor growth was determined in vivo." (PMID 33817293, 2021). "However, the addition of PVT1 weakened the suppressive effect of gemcitabine on tumor growth." (PMID 32727463, 2020). "In fact, several lncRNAs such as HOTAIR (homebox C transcript antisense RNA) or PVT1 (lncRNA plasmacytoma variant translocation 1) behave as oncogenes, whereas others such as MEG3 (maternally expressed 3) or PANDAR (promoter of CDKN1A antisense DNA damage-activated RNA) act as tumor suppressors." (PMID 32214045, 2020). "In addition, the PVT1 promoter also has tumor suppressor activity independently of the PVT1 lncRNA." (PMID 33134177, 2020). "In addition, PVT1 promotes colon cancer cell proliferation through releasing the inhibitory effect of miR-30d-5p on RUNX2, a crucial transcription factor associated with tumor cell growth, proliferation and metastasis." (PMID 31497532, 2019). "In addition, the coexpression of lncRNAs and tumorigenesis gene (well-known oncogene MYC and lncRNA Pvt1) is found in various tumors, which suggests that lncRNAs may have an important direct relationship with tumor growth." (PMID 31850199, 2019). "In addition, PVT1 also downregulates the expression of miR-146a by increasing the activity of DNA methylase, which induces the methylation of the CpG island in miR-146a precursor, thereby affecting the growth of tumor cells." (PMID 31380270, 2019).
tumor (continued). "Multiple miRNA response elements are found on PVT1, to which specific miRNAs can bind and such that these miRNAs are silenced and the expression of certain proteins are upregulated, which ultimately affects the proliferation, invasion, and drug resistance of tumor cells." (PMID 31380270, 2019). "GSEA revealed that overexpression of PVT1 may be involved in the posttranscriptional regulation of gene expression, tumor invasiveness and metastasis, osteoblast differentiation and development, apoptosis, nuclear factor kappa B, Wnt, and apoptotic related signaling pathways." (PMID 31598169, 2019). "Certain mechanisms through which PVT1 affects tumor development remain unclear." (PMID 31380270, 2019). "In addition, specific miRNA analogs combined with reduction of PVT1 expression are able to even further reduce tumor growth, suggesting that miRNAs may collaborate with PVT1 to regulate tumor progression." (PMID 31249809, 2019). "Focusing on the PVT1 chromosome interval representing circPVT1, we did not observe any difference between tumor samples with either FAT1 or CDKN2A mutations and those with an intact FAT1 or CDKN2A gene, which were both up-regulated in comparison to non-tumoral samples." (PMID 29262850, 2017). "However, the precise mechanism of how PVT1 promotes tumor progression is unclear." (PMID 29348896, 2017). "Hence, our results suggest that promoter hypomethylation is an important cause of PVT1 up-regulation in tumor patients lacking 8q24 locus amplification." (PMID 27366943, 2016). "Furthermore, supporting the impact of PVT1 in the clinical outcome of KIRC patients, we observed that high expression levels were significantly associated with neoplasm status after surgery and advanced clinical stage or metastasis (Fisher's Exact -test p-value < 0.05)." (PMID 27366943, 2016). "Thus, the findings of the present study indicate that PVT1 may act as a novel biomarker for predicting tumor recurrence in HCC patients and may be a potential therapeutic target." (PMID 25624916, 2015). "Thus, the high expression levels of PVT1 in HCC may serve as a novel biomarker for predicting tumor recurrence in HCC patients, and as a potential therapeutic target." (PMID 25624916, 2015). "Our analysis of RNA-Seq data from diverse MB tumor subtypes revealed PVT1 fusions to be most prevalent in G3 gamma, a subtype featuring MYC-PVT1 amplification and PVT1 translocation, as well as in G3 alpha." (PMID 40027648, 2025). "lncRNAs have emerged as critical regulators in CC progression, as exemplified by well‐characterized oncogenic and tumor‐suppressive lncRNAs such as HOTAIR and PVT1." (PMID 40665897, 2025). "SNHG6 was expressed at the tumor edge and in the pseudopalisading regions around necrosis, but most lncRNAs (Pvt1, SNHG12, H19, Neat1, Malat1, Mir17hg and Ftx) were expressed around the necrotic tumor regions." (PMID 40527978, 2025). "FAM171A2 transcripts showed strong negative correlations with the tumor-suppressor miR-15/16 family and with tumor-promoting lncRNAs such as UCA1 and PVT1." (PMID 41303609, 2025). "According to the UALCAN database, the expression levels of PVT1, hsa-miR-143–3p, CDK1, FOXC1, YY1, and GATA2 show statistically significant differences between primary tumor samples and normal samples in the TCGA-LUAD dataset." (PMID 41080754, 2025). "Besides, PVT1 may contribute to tumor development independently of MYC." (PMID 38994720, 2024). "To further investigate the oncogenic role of PVT1 in GBM in vivo, we established a tumor xenograft model." (PMID 38287522, 2024). "Another notable lncRNA, PVT1, facilitates the EMT in UM, a pivotal step for tumor invasion and metastasis." (PMID 39353898, 2024). "Other examples of lncRNAs secreted from tumor exosomes include LUCAT1 and PVT1 in exosomes of liver cancer." (PMID 39512820, 2024).